ABCB11 (ATP binding cassette subfamily B member 11)
Diseases named in the same sentence as ABCB11 in open-access papers (continued):
Sharing a sentence is not in itself a finding about the gene and the disease.
progressive familial intrahepatic cholestasis (18 papers, 2014 to 2025). Progressive familial intrahepatic cholestasis (PFIC) refers to a heterogeneous group of autosomal recessive disorders of childhood that disrupt bile formation and present with cholestasis of hepatocellular origin. "Hereditary cholestatic syndromes in children, clinically presenting as progressive familial intrahepatic cholestasis (PFIC) types 1–3, result from mutations of ATP8B1, ABCB11, and ABCB4." (PMID 28626473, 2017). "Progressive familial intrahepatic cholestasis (PFIC) is caused by variations in ATP8B1, ABCB11 or ABCB4 genes." (PMID 29973134, 2018). "Genetic testing should also be considered such as mutations in the hepatobiliary transporters ATP8B1, ABCB11 and ABCB4 in the evaluation of familial hepatocellular cholestasis like progressive familial intrahepatic cholestasis (PFIC) or benign recurrent intrahepatic cholestasis (BRIC)." (PMID 39600379, 2023). "Owing to a combination of biochemistry, physiology, genetics and clinical science, the roles of three transporters: lipid floppase, ABCB4, bile salt export pump, ABCB11 and the P-type ATPase, ATP8B1 in progressive familial intrahepatic cholestasis (PFIC) are now well understood." (PMID 26517919, 2015).
benign recurrent intrahepatic cholestasis (17 papers, 2013 to 2025). Benign recurrent intrahepatic cholestasis (BRIC) is a hereditary liver disorder characterized by intermittent episodes of intrahepatic cholestasis, generally without progression to chronic liver damage. "Among the pathways related to ABC protein transporters, the defective ABCB11 pathway causes benign recurrent intrahepatic cholestasis type 2 (BRIC2) was highly enriched in our results." (PMID 39598509, 2024). "Benign recurrent intrahepatic cholestasis (BRIC) is a disease on the spectrum of familial intrahepatic cholestasis caused by homozygous ABCB11 or ATP8B1 mutations." (PMID 37205944, 2021). "The bile salt export pump (BSEP), encoded by the gene ABCB11, (ATP binding cassette subfamily B member 11) is homozygously mutated in PFIC type 2 and benign recurrent intrahepatic cholestasis (BRIC) type 227." (PMID 28924228, 2017). "In addition, depending on the severity of the disease, inherited intrahepatic cholestasis resulting from mutations in ATP8B1 or ABCB11 can be classified as either PFIC1 or 2, respectively, or benign recurrent intrahepatic cholestasis (BRIC) 1 or 2, respectively." (PMID 35740260, 2022).
familial intrahepatic cholestasis (16 papers, 2013 to 2025). An instance of intrahepatic cholestasis that is caused by an inherited modification of the individual's genome. "For example, ABCB11 or ATP8B1 causing progressive familial intrahepatic cholestasis; other genes might lead to liver abnormalities that are presenting clinically as a secondary cause." (PMID 38057357, 2023). "Mutations in the ATP8B1, ABCB11 and in the ABCB4 genes encoding ATP8B1, BSEP and MDR3 respectively, have been linked to progressive familial intrahepatic cholestasis." (PMID 36430444, 2022). "Genes associated with familial intrahepatic cholestasis (FIC) include ATP8B1 (FIC1), ABCB11 (FIC2), ABCB4 (FIC3), TJP2 (FIC4), NR1H4 (FIC5) and MYO5B (FIC6)." (PMID 33557414, 2021). "Disruption of expression of these transporters is pathologic as evidenced by inherited mutations of ABCB11 and ABCC2 which cause progressive familial intrahepatic cholestasis and Dubin–Johnson disease, respectively." (PMID 29643332, 2018).
gallstones (16 papers, 2009 to 2025). Solid crystalline precipitates in the biliary tract, usually formed in the gallbladder, resulting in the condition of cholelithiasis. "Polymorphisms in ABCB11 have been implicated in gallstone pathogenesis, yet evidence from Middle Eastern populations, particularly Iran, remains limited." (PMID 42038875, 2025). "Our findings add to the existing body of research on ABCB11 variants and gallstones, as previously documented in seven Dutch patients." (PMID 41436587, 2025). "To date, it has been discovered that the CYP27A1, LXR, PPAR-α, ABCG8 and ABCB11 genes involved in lipid metabolism predispose an individual to gallstone formation." (PMID 32615989, 2020). "In a gallstone model, PKCα activation down‐regulates the bile acid transporter protein ATP‐Binding cassette subfamily B member 11 (ABCB11), which is directly associated with disturbed bile metabolism and promotes cholesterol crystallization and gallstone formation." (PMID 41244006, 2025). "2/9 (22.2%) had a known diagnosis of gallstones both of whom had an ABCB11 variant." (PMID 41436587, 2025). "Of the 26 women with a mutation in a biliary transporter (ABCB4, ABCB11, APT8B1, ABCC2), 12 (46%) had an established family history of biliary disease (ICP, cirrhosis or gallstones)." (PMID 28924228, 2017). "Henkel and Wei (2005) observes that overexpress BESP (ABCB11) in mice fed a lithogenic diet have an increased rate of cholesterol crystal and gallstone formation." (PMID 25107305, 2014). "BRIC Type 1 and Type 2 are important differential diagnosis we should should consider with our participants with ABCB11 LoF (a1044x, c.2611-2 A > T, W239x) and ABCB11 SNV R1050H, especially since BRIC Type 2 has shown to have a correlation with gallstones." (PMID 41436587, 2025). "Additionally, the downregulated proteins in gallstone bile showed enrichment in bile acid and bile salt transport (padjusted = 0.004), which included AKR1C1, ABCC2, ABCB11, and ATP8B1." (PMID 38111640, 2023). "Thus, increasing the expression levels of ABCG8, ABCB11, CYP7A1 and CYP27A1 or decreasing the levels of LXR and PPAR-α can stimulate bile acid secretion and efficiently facilitate gallstone dissolution to reverse damage to the hepatocytes." (PMID 32615989, 2020). "Nevertheless, recent data from sib pairs with gallstones and control do not support a link between ABCB4 and ABCB11 polymorphisms and gallstone formation in the large majority of patients." (PMID 25107305, 2014).
Cirrhosis (15 papers, 2012 to 2025). A chronic disorder of the liver in which liver tissue becomes scarred and is partially replaced by regenerative nodules and fibrotic tissue resulting in loss of liver function. "To assess a potential impact of the ABCB11 c.1331 risk genotype [CC] on cirrhosis, we performed univariate and multivariate logistic regression analyses." (PMID 22681771, 2012). "PFIC type 2 is characterized by a genetic defect in the bile acid transporter bile salt export pump (BSEP) encoded by ABCB11, and results in HCC via development of cirrhosis." (PMID 39941018, 2025). "Previously, it has been described that ABCB11 c.1331T>C is associated with biopsy-proven liver fibrosis and cirrhosis in patients with HCV but not in NAFLD." (PMID 37511794, 2023). "Histologically, PFIC3 is characterized by portal inflammation, fibrosis, progression to cirrhosis, and unlike PFIC2 (another type of progressive familial cholestasis characterized by mutations in the ABCB11 gene encoding BSEP), bile ducts are highly proliferative in PFIC3." (PMID 36733378, 2022).
hepatocellular carcinoma (15 papers, 2014 to 2025). A malignant tumor that arises from hepatocytes. "In WIF-B9 cells, a hybrid cell line derived from human hepatoma and rat fibroblasts that exhibits hepatocyte-like properties, ABCB11 localizes to tubulovesicular structures that migrate toward both membrane poles but fuse only at the canalicular surface." (PMID 41428126, 2025). "Deficiency in ABCB11 (PFIC2) show a complicated clinical expectation as the disease is cell autonomous and patients can develop hepatocellular carcinomas (HCC) or cholangiocarcinoma’s (CCC)." (PMID 33383947, 2020). "Furthermore, in vitro experiments in primary mouse hepatocytes and human hepatoma cell lines HuH7 and HepG2 together with in vivo experiments demonstrated that IL-1β exposure was sufficient to suppress transcription of Nr1h4, Abcb11, Abcc2, and Abcg5/8, findings that characterize the PNAC liver." (PMID 29643332, 2018). "However, HepaRG cells remain transformed hepatoma cells, which express at low level certain detoxifying proteins present in human hepatocytes, such as the cytochromes P-450 1A2, 2D6 and 2E1 and the drug transporters OATP1B3 (SLCO1B3) and bile salt export pump (BSEP/ABCB11)." (PMID 30469356, 2018).
liver fibrosis (15 papers, 2012 to 2026). "2/2 (100%) of cases with hepatic fibrosis had an ABCB11 LoF variant." (PMID 41436587, 2025). "Moreover, polymorphisms such as rs2109505 (c.711A>T, p.I237=) in ABCB4 and rs2287622 (c.1331T>C, p.V444A) in ABCB11 are more prevalent in adult patients with idiopathic cholestasis than in healthy controls representing risk factors for the development of liver fibrosis." (PMID 35884482, 2022). "In mice lacking the major hepatic excretory system for bile acids (BAs), bile salt export pump (Bsep/Abcb11), accumulation of hydrophilic BAs mitigates hepatic schistosomiasis (liver fibrosis and inflammation)." (PMID 37641872, 2023). "Our data confirm that homozygous presence of the major [C] allele of ABCB11 c.1331 T > C is a genetic susceptibility factor for HCV infection, but not for liver fibrosis." (PMID 22681771, 2012).
liver failure (12 papers, 2017 to 2025). A liver disease characterized by the liver losing or has lost all of its function. "In this study, we report a case with severe liver failure due to BA combined with Wilson disease and carried a homozygous variant in the ABCB11 gene." (PMID 35029214, 2022). "A genetic deficiency in bile salt export protein (BSEP, ABCB11) is associated with severe cholestatic liver injury resulting in liver failure in infancy." (PMID 33799477, 2021). "PFIC represents a group of disorders (with subtypes grouped based on the underlying genetic deficiency; eg ATP8B1‐deficient PFIC, ABCB11‐deficient PFIC) in which disruption of bile homeostasis can eventually lead to cholestasis, cirrhosis, liver failure and death." (PMID 32492754, 2020). "In this regard, it has been found that in humans, a defect in the ABCB11 gene encoding BSEP leads to progressive familial intrahepatic cholestasis-II, which clinically manifests as an elevation in transaminase levels and subsequent development of hepatic failure." (PMID 40243350, 2025).
benign recurrent intrahepatic cholestasis type 2 (10 papers, 2013 to 2025). "BRIC type 1 is associated with mutations in the ATP8B1 gene, while BRIC type 2 is linked to mutations in the ABCB11 gene." (PMID 39735080, 2024).
Obesity (10 papers, 2012 to 2025). Accumulation of substantial excess body fat. "Hepatic overexpression of Abcb11 encoding for BSEP in mice has been shown to promote high-fat diet-induced obesity, as well as high-cholesterol diet-induced hypercholesterolemia, and it may thus be interesting to study the relation between BSEP and plasma lipids in more depth." (PMID 35011746, 2021). "The development of diet-induced obesity and hypercholesterolemia following hepatocye-specific overexpression of ABCB11 in mice is a pointer in the same direction." (PMID 22681771, 2012). "GCKR, ABCB11, CDKAL1, CDKN2B, NT5C2, and APOC1 were associated with metabolically unhealthy in individuals with normal weight but not in those with obesity." (PMID 33500527, 2021). "GCKR, ABCB11, CDKAL1, CDKN2B, NT5C2, and APOC1 were associated with metabolically unhealthy phenotypes in individuals with normal weight but not in those with obesity." (PMID 33500527, 2021). "He found GCKR, ABCB11, CDKAL1, CDKN2B, NT5C2, and APOC1 gene were associated with metabolically unhealthy phenotypes in individuals with normal weight but not in those with obesity, showing that certain genetic polymorphisms may also have an impact on the metabolic health in NWO populations." (PMID 39777912, 2025).
cholangiocarcinoma (9 papers, 2010 to 2025). A carcinoma that arises from the intrahepatic biliary tree (intrahepatic cholangiocarcinoma) or from the junction, or adjacent to the junction, of the right and left hepatic ducts (hilar cholangiocarcinoma). "Thus, at least in regard to HCC and cholangiocarcinoma, the ABCB11 gene defect appears to be an independent risk factor." (PMID 20226067, 2010).
Hepatic steatosis (9 papers, 2011 to 2025). Steatosis is a term used to denote lipid accumulation within hepatocytes. "Indeed, overexpression of Abcb11 in the liver is sufficient to decrease HFD-induced liver steatosis by increasing lipid secretion into the bile." (PMID 36586437, 2023). "Also, in a transgenic Abcb11 overexpression model, increased liver Abcb11 expression showed ameliorating effects on hepatic steatosis by increasing excretion of biliary phospholipids and cholesterol." (PMID 21291556, 2011). "4/6 (66.6%) of cases with hepatic steatosis had an ABCB4 LoF and 2/6 (33.3%) had an ABCB11 LoF or SNV." (PMID 41436587, 2025).
Alagille syndrome (6 papers, 2016 to 2024). "NGS of high C-triol infants identified three patients with mutations in JAG1 (Alagille syndrome) and ABCB11 (Byler disease) genes." (PMID 31296176, 2019). "Genetic examination identified 11 cases of genetic disorders: Dubin–Johnson syndrome in 2, citrin deficiency in 2, Alagille syndrome in 2, trisomy 21 in 2, bile acid synthesis defects in 1, and two genetic variants of unknown diagnostic significance (e.g., ATP11C and ABCB11) in 2 patients." (PMID 36405823, 2022).
Byler disease (6 papers, 2015 to 2023). "There was one patient with progressive familial intra‐hepatic cholestasis type 1 (no genetic confirmation available; diagnosed in 1992) and one patient with BSEP deficiency (confirmed mutation in ABCB11)." (PMID 35762110, 2022).
Dubin-Johnson syndrome (6 papers, 2014 to 2022). Dubin-Johnson syndrome (DJS) is a benign, inherited liver disorder characterized clinically by chronic, predominantly conjugated, hyperbilirubinemia and histopathologically by black-brown pigment deposition in parenchymal liver cells. "These include ABCA1 (HDL-deficiency, Tangier disease), ABCB4 (progressive familial intrahepatic cholestasis type 3; PFIC3), ABCB11 (PFIC2), ABCC2 (Dubin-Johnson syndrome), ABCC6 (pseudoxanthoma elasticum, general arterial calcification of infancy) and ABCG2 (gout)." (PMID 24316454, 2014).
injury (6 papers, 2013 to 2024). Damage inflicted on the body as the direct or indirect result of an external force, with or without disruption of structural continuity. "In conclusion, we found that genetic polymorphism of ABCB11 might contribute to ATDs-induced cholestatic liver injury in Chinese population." (PMID 27293027, 2016).
liver cirrhosis (6 papers, 2012 to 2022). "Of note, variants of the human bile salt that export pump ABCB11 might be associated with sustained virological response and progression towards liver cirrhosis." (PMID 22523693, 2012).
chronic hepatitis C (4 papers, 2012 to 2019). "One patient with chronic hepatitis C showed inhomogeneous, weak expression of ABCB11 and ABCB4, and one FNH patient, accumulation of ABCB4 in some areas, but a homogeneous expression of ABCB11 at the bile canalicular membrane of adjacent hepatocytes (Supplementary and Supplementary )." (PMID 31886153, 2019).
primary sclerosing cholangitis (4 papers, 2014 to 2025). "It has been suggested recently that genetic variants of ABCB11 and ABCB4 could be involved in the pathogenesis of primary sclerosing cholangitis (PSC)." (PMID 31886153, 2019).
Wilson disease (4 papers, 2021 to 2025). A very rare inherited multisystemic disease presenting non-specific neurological, hepatic, psychiatric or osseo-muscular manifestations due to excessive copper deposition in the body. "This study also documented downregulation of ABCB11 and encoded BSEP transporter levels in Wilson’s disease subjects." (PMID 34117631, 2021). "For inherited diseases such as PFIC1, PFIC2, PFIC3, and Wilson’s disease, the coding regions of the ATP8B1, ABCB11, ABCB4, and ATP7B sequences exceed the AAV vector capacity." (PMID 39684224, 2024).
atherosclerosis (3 papers, 2024 to 2025). A disease characterized by the build-up of fatty material and calcium deposition in the arterial wall resulting in partial or complete occlusion of the arterial lumen. "Of the 25 shared novel atherosclerosis loci with evidence of colocalization, 7 analyses strongly colocalized with PRPA ≥0.80 (nearest gene: BNC2, SCAI, TSC22D2, SRRM1, ABCB11, PRRX2)." (PMID 40313769, 2025).
biliary atresia (3 papers, 2021 to 2023). A rare, biliary tract disease characterized by progressive obliterative cholangiopathy of the intra- and extrahepatic bile ducts, occurring in the embryonic/ perinatal period, leading to severe and persistent neonatal jaundice and acholic stool. "ABCB11 mRNA was also significantly depleted and miR-199a-5p was elevated over fourfold in livers of infants with biliary atresia at the time of Kasai portoenterostomy compared with normal livers." (PMID 34774795, 2021). "The downregulation of ABCB11 early in the course of biliary atresia agrees with a previous study." (PMID 34774795, 2021). "Similarly, as confirmed in this study, early in the course of biliary atresia in infants, most canalicular transporters are downregulated, including bile salt export pump (BSEP, ABCB11), multidrug-resistant protein 3 (MDR3, ABCB4), and the multidrug-resistant associated protein 2 (MRP2, ABCC2)." (PMID 34774795, 2021).
cholelithiasis (3 papers, 2007 to 2025). The presence of crystallized deposits forming in the gallbladder or biliary tree, primarily composed of cholesterol, bilirubin, and bile. "Genes such as ABCG5/G8, ABCB4, ABCB11, and UGT1A1 are crucial in increasing the lithogenicity of bile and are strongly associated with various forms of cholelithiasis, especially cholesterol-based." (PMID 40149408, 2025).
diabetes (3 papers, 2017 to 2024). "Similarly, genes ABCB11 (chromosome 2), ADCY5 (chromosome 3), CDKAL1 (chromosome 6), ANK1 (chromosome 8), GLIS3 (chromosome 9), and HKDC1 (chromosome 10) have been linked to various aspects of diabetes, including insulin release, glucose levels, β-cell function, and insulin resistance." (PMID 38274506, 2023).
gout (3 papers, 2014 to 2019). A condition characterized by painful swelling of the joints, which is caused by deposition of urate crystals. "Screens for small molecule treatments have been instigated, including for Tangier disease (ABCA1), gout (ABCG2), Stargardt eye disease (ABCA4), progressive familial intrahepatic cholestasis type 2 (ABCB11), and congenital hyperinsulinemia." (PMID 30659068, 2019).
liver cancer (3 papers, 2016 to 2025). An epithelial or non-epithelial malignant neoplasm that arises from the liver. "ABCB11 (PFIC2) variants present an enhanced risk of developing liver cancers, as shown in the NAPPED study." (PMID 39984942, 2025). "Mutations in ABCB11 which causes deficiency of ABCB11 increase the risk of liver cancer." (PMID 28119610, 2016).
ovarian carcinoma (3 papers, 2019). A malignant neoplasm originating from the surface ovarian epithelium. "Moreover, previous studies also demonstrated a critical role for ABCB11 in lung and ovarian cancer." (PMID 31889904, 2019).
breast carcinoma (2 papers, 2021 to 2022). "In addition, ABCB11 mutations are prevalent in the DNA of patients with primary breast cancers and are considered to be associated with tumour prognosis." (PMID 34178671, 2021). "For metformin, the highest number of its targets were associated with malignant neoplasm of the prostate (six genes) and breast carcinoma (seven genes: ABCB11; ABCC2; ABCC3; ABCC4; DHFR; DPP4; SLC22A1)." (PMID 36046822, 2022).